Y_RNA (Y RNA )
Gene: Miscellaneous RNA gene on chromosome 8 (68,223,318 to 68,223,402, reverse strand). Ensembl gene ENSG00000252210.
Homologues: Orthologues: chimpanzee Y_RNA (99% identical), macaque Y_RNA (92% identical). Paralogues in human: Y_RNA (76% identical), RNY1 (75% identical), Y_RNA (75% identical), RNY1P8 (74% identical), Y_RNA (74% identical), RNY1P7 (73% identical), Y_RNA (73% identical), Y_RNA (72% identical), RNY1P11 (71% identical), Y_RNA (71% identical), RNY1P10 (69% identical), RNY1P12 (69% identical), and 88 more.